ACTA1 (actin alpha 1, skeletal muscle)
Diseases named in the same sentence as ACTA1 in open-access papers (continued):
Sharing a sentence is not in itself a finding about the gene and the disease.
cardiac hypertrophy (35 papers, 2014 to 2025). "Bulk RNA sequencing revealed significant upregulation of several biomarkers associated with cardiac hypertrophy in BubR1 hypomorphic hearts, including Thbs4, Acta1, Tnni2, and Myh7." (PMID 40607964, 2025). "Myocyte size was greater and there was increased expression of genes associated with cardiac hypertrophy (Anp, Acta1 and β-MHC)." (PMID 35406763, 2022). "Re-expression of ACTA1 that encodes α-smooth muscle actin has been associated with cardiac hypertrophy in vitro and in vivo, in animal models and humans." (PMID 25051449, 2014). "ACTA1, a contractile fiber gene, is associated with heart failure and cardiac hypertrophy." (PMID 33062700, 2020). "Although cardiac involvement is rare, some reported cases associate ACTA1 variants with cardiac conditions such as dilated cardiomyopathy (DCM) and hypertrophy, often occurring jointly with myopathy." (PMID 40428316, 2025). "The expression levels of fetal genes, including Nppa, Nppb, and Acta1, which are often elevated in cardiac hypertrophy, were further increased in METTL5-cKO TAC hearts." (PMID 35295259, 2022). "Next to cell-cycle genes, genes involved in cardiac hypertrophy such as Acta1 and Hdac5 were also expressed higher in cKO mice." (PMID 33917189, 2021). "Among them, Csrp3, Pdlim5, Sorbs2, Rcan1, and Acta1, which were related to cardiac hypertrophy and remodeling, were upregulated and modified by at least one active histone mark." (PMID 33330655, 2020). "The mRNA levels of atrial natriuretic peptide (ANP), brain natriuretic peptide (BNP), and skeletal α-actin (ACTA1), key markers of cardiac hypertrophy and injury, were significantly upregulated in the P407 group and effectively reduced by HAE supplementation." (PMID 31936037, 2020). "ACTA1 is a member of the “fetal" gene profile typically increased in pathological cardiac hypertrophy and downregulated in exercise‐induced physiological hypertrophy (Vega, Konhilas, Kelly, & Leinwand, 2017)." (PMID 32441410, 2020). "The muscle-specific miR-133 has critical functions in the heart and is a powerful inhibitor of cardiac hypertrophy and the transcription factor SRF is an important regulator of several hypertrophy associated genes, such as Nppa, Nppb and Acta1." (PMID 26919721, 2016). "Cardiac hypertrophy goes along with the upregulation of mRNA levels of the natriuretic peptides A (Nppa) and B (Nppb) and the cytoskeletal protein skeletal alpha actin (Acta1) in the myocardium." (PMID 26919721, 2016). "As expected, PE stimulation significantly produced cardiac hypertrophy, which was associated with an increased size of cardiomyocytes and increased mRNA levels of BNP, β‐MHC, and ACTA1." (PMID 27416746, 2016). "For example, we observed deregulation of chamber-specific factors (e.g. Myh7, Bmp7, Anf, Acta1, Egr1 and Fos) that are also upregulated in adult cardiac hypertrophy and/or heart failure." (PMID 25803368, 2015). "Cardiac fetal genes (NPPA, NPPB, MYH6, MYH7 and ACTA1) are usually only expressed during fetal life and re-expression of these genes in adult life is an indicator of pathologic cardiac hypertrophy." (PMID 25051449, 2014). "More molecular studies confirmed that empagliflozin ameliorates the expression of cardiac hypertrophy markers such as actin alpha (ACTA1), four-and-a-half LIM domains 1 (FHL1), myosin light chain 2a (MLC2A) in high-glucose-exposed human-induced pluripotent stem cells-derived cardiomyocytes." (PMID 36552708, 2022). "Recently, Acta1 has been associated with cardiac hypertrophy through increased levels of IGF‐1, so the reduced levels of Acta1 in NLRP3−/− mice could be associated with the reduced serum levels of IGF‐1 shown in this study." (PMID 31625260, 2020).
cardiac hypertrophy (continued). "In line with the observed hypertrophic changes, high glucose treatment significantly increased the expression of the cardiac hypertrophy markers ACTA1 (HG vs NG: about 6.0 fold, p < 0.01), FHL (HG vs NG: about 3.9 fold, p < 0.01) and MLC2A (HG vs NG: about 3.5 fold, p < 0.01)." (PMID 30291295, 2018). "Similarly regulated transcripts between previous studies utilizing TAC-induced cardiac hypertrophy and this study include Acta1, MybpC2/3, Actn2, and Myh7 among others indicating an appropriate hypertrophic gene transcriptional response in WT mice." (PMID 26192751, 2015). "Both groups of mice developed a comparable degree of cardiac hypertrophy in response to TAC, as shown by similarly enhanced HW/TL ratio, embryonic gene expression (decrease in Myh6 and Atp2a2, increase in Myh7 and Acta1 mRNA) and cardiomyocyte size." (PMID 35013221, 2022). "qRT-PCR showed that cardiac hypertrophy-related markers including ANP, ACTA1 and MYH7 were significantly elevated in miR-26a-5p agomir group compared to controls." (PMID 33240671, 2020). "GSK3β overexpression significantly reversed the expression of cardiac hypertrophy-related markers including ANP, ACTA1 and MYH7." (PMID 33240671, 2020). "We further observed the effects of miR-26a-5p on cardiac hypertrophy-related markers including ANP, ACTA1 and MYH7." (PMID 33240671, 2020). "miR-26a-5p dramatically promoted PE-induced increase in cardiac hypertrophy-related markers including ANP, ACTA1 and MYH7." (PMID 33240671, 2020). "In our mouse and cell models of cardiac hypertrophy, myocardial cell size and the levels of BNP, β‐MHC, and ACTA1 were all increased after exposure to Ang II or PE." (PMID 27416746, 2016). "Furthermore, the induction of cardiac atrophy by DOX was observed, as determined by RT‐PCR detection, along with a suppression of markers for cardiac hypertrophy, namely β‐myosin heavy chain (β‐MHC) and actin α1 (ACTA1) mRNA expression." (PMID 40785055, 2025). "Cardiac hypertrophy and remodeling are also crucial early adaptative steps (before becoming pathological), which are accompanied by the re-expression of the fetal gene program comprising NPPA, ACTA1, and MYH7." (PMID 37445625, 2023). "Moreover, HAE treatment significantly downregulated mRNA levels of cardiac hypertrophy and injury markers ANP, BNP, and ACTA1, which were all highly induced by P407." (PMID 31936037, 2020). "Furthermore, miR-26a-5p agomir significantly promoted cardiac hypertrophy-related markers including ANP, ACTA1 and MYH7." (PMID 33240671, 2020). "Furthermore, CYP2J2 overexpression ameliorated Ang II‐induced expression of the biomarkers of cardiac hypertrophy brain natriuretic peptide (BNP), β‐myosin heavy chain (β‐MHC), and skeletal muscle α‐actin (ACTA1)." (PMID 27416746, 2016). "ACTA1, MYH7, and SERCA2 are well-known markers for cardiac hypertrophy." (PMID 26108756, 2015). "In our study, the ‘fetal’ genes including BNP, β-MHC and ACTA1 levels were strongly increased in lenti-GFP treated hearts, and reduced in lenti-99a-GFP group, further supporting our observation that miR-99a overexpression attenuated cardiac hypertrophy and heart failure." (PMID 26914935, 2016). "However, overexpression of Ufm1 in hearts failed to vary ISO-induced HW/BW ratio and Acta1 increase, indicating that Ufm1 overexpression were not able to vary ISO-induced cardiac hypertrophy." (PMID 37980507, 2023).
heart failure (29 papers, 2015 to 2025). Inability of the heart to pump blood at an adequate rate to meet tissue metabolic requirements. "RT-qPCR analysis revealed that cardiac fetal genes including Acta1, Myh7, Nppb, and Nppa, which are associated with heart failure, were significantly increased in GsαCMKO mice." (PMID 34907172, 2021). "Heart histological staining and mRNA levels of genes associated with heart failure (Acta1 and Nppa), inflammation (IL‐6), and fibrosis (Ctgf, Col1a2, Timp1, and Mmp9) were assessed." (PMID 32133617, 2020). "ACTA1 expression in the cardiovascular systems can serve as a marker of pathological hypertrophy, associated cardiac diseases, and, ultimately, heart failure." (PMID 35805966, 2022). "Myocardial tissue also showed upregulation of ANP (Nppa), BNP (Nppb), and Acta1 genes, associated with progression to cardiac failure, but congestive heart failure appeared unlikely because there was no accompanying change in peripheral oxygen saturation, heart rate, or tissue edema." (PMID 31805812, 2020). "Importantly, adenoviral overexpression of glypican-6 in cultured cardiomyocytes increased protein synthesis and induced mRNA levels of the pro-hypertrophic signature gene ACTA1 and the hypertrophy and heart failure signature genes encoding natriuretic peptides, NPPA and NPPB." (PMID 27768722, 2016). "Early hallmarks of heart failure, including skeletal muscle α-actin (Acta1) and brain natriuretic peptide (Nppb) were upregulated in KO hearts." (PMID 38950288, 2024). "Another upregulated gene was α-actin 1, encoded by ACTA1, which has been shown to be increased in LVH and heart failure both in rodents and in humans." (PMID 33802976, 2021). "We found a significant upregulation of cardiac tissue CXCR4 mRNA, which has been shown to prevent adaptive ventricular remodelling after pressure overload and increased ACTA1 levels, that has been shown to be a marker for heart failure." (PMID 33802976, 2021). "Elevated ACTA1 expression has been reported in human heart failure samples and in a model mouse of DCM." (PMID 32236096, 2020). "AAV-HDAC1/2 also restored repression of slow twitch sarcomere genes Acta1 and Myh7, and reduced expression of the heart failure marker Nppa." (PMID 28394251, 2017). "We further verified that the mRNA levels of heart failure–related genes (Nppa, Nppb, and Acta1) in cardiomyocytes transduced with Myc both under serum-supplemented conditions and serum-free conditions." (PMID 27346836, 2016). "In support of the functional data, levels of the heart failure marker Acta1 were significantly reduced with AAV9.IGF-1Ea treatment." (PMID 29302333, 2016). "High-dose EPO also increased heart failure-associated genes such as Cdk8, Nox4, S100A, and SERCA2a, and hypertrophic cardiomyopathy-related genes such as Acta1, Myh7, Nppa, and Nppb in male WT mice but not in ΔEPORE male mice." (PMID 38628440, 2024). "Furthermore, the expression of heart failure marker ACTA1 was significantly increased in VEGFR-1 TK−/− mice." (PMID 33802976, 2021). "Heart failure is associated with the reactivation of fetal genes, including atrial natriuretic peptide (ANP; Nppa), brain natriuretic peptide (BNP; Nppb), and skeletal α-actin (Acta1), associated with structural and functional remodeling of the heart." (PMID 32384912, 2020). "Changes in α-skeletal actin (Acta1–6 fold increase), atrial natriuretic peptide (Nppa– 1.9 fold increase), brain natriuretic peptide (Nppb– 2.6 fold increase), cardiac troponinT (cTnT– 14% decrease), consistent with expected molecular signature of heart failure." (PMID 30811446, 2019). "PCR also showed that heart failure markers (ANP, BNP, β-MHC, and Acta-1) were higher in the WT + Dox group than in the WT + Saline group." (PMID 35991177, 2022). "We found that 5 mg/kg body weight of ISO treatment for 5 days was sufficient to increase the HW/BW ratio and expression of hypertrophy biomarker Acta1, but did not increase heart failure biomarkers, such as Anp and Bnp." (PMID 37980507, 2023).
heart failure (continued). "It has been concluded that increasing ACTA1 in heart failure is to compensate for contraction failure, irrespective of cause." (PMID 32236096, 2020).
congenital myopathies (23 papers, 2011 to 2026). "Pathogenic variants in ACTA1 cause congenital myopathy with a wide range of clinical variability, ranging from death in infancy to a survival in adulthood." (PMID 38316882, 2024). "Early involvement of the sartorius muscle has also been described in patients with mutations in SPEN1, RYR1, TNPO3, and MYH7, in some congenital myopathies like ACTA1, and in myofibrillar myopathies with mutations in DES or CRYAB." (PMID 35286480, 2022). "The G151E mutation is analogous to a dominant allele in ACTA1 in a human patient with severe congenital myopathy where it resulted in abnormal actin aggregates." (PMID 30694177, 2019). "In Feng’s review thirty congenital myopathy-causing ACTA1 mutations were analysed using a range of biochemical and in vitro approaches." (PMID 29997361, 2018). "Mutations in ACTA1 can interfere with the function, assembly and stability of the fine filaments resulting in different overlapping congenital myopathies, including NM." (PMID 30517146, 2018). "ACTA1 gene mutations have been shown to cause congenital myopathies." (PMID 34648569, 2021). "Some reports have demonstrated that ACTC1 over-expression in postnatal skeletal muscle could effectively rescue ACTA1-related diseases, congenital myopathies caused by mutations in ACTA1." (PMID 29324704, 2018). "Mutation of ACTA1 results in various types of congenital myopathy." (PMID 25890230, 2015). "Notably, three muscle-specific genes, ACTA1, TPM3, and CLCN1, were associated with hereditary skeletal myopathy and congenital myopathy." (PMID 41297061, 2025). "Additionally, variations in genes associated with nemaline myopathy (NEM1, ACTA1, TPM3) should be considered and screened as part of a NGS congenital myopathy sequencing panel to identify causative variants." (PMID 30406384, 2018). "At the clinical level there is a growing body of anecdotal evidence to suggest that exercise may be beneficial for patients with congenital myopathies, including ACTA1 congenital myopathies." (PMID 22174871, 2011). "Comparison of involvement patterns with literature datasets highlighted preferential adductor and gracilis sparing in our ACTA1‐NM cohort, consistent tibialis posterior involvement in our TPM3‐NM cohort and a distinct MRI pattern from those derived from other NM genotypes and congenital myopathies." (PMID 37265148, 2023).
cardiomyopathy (16 papers, 2007 to 2025). A disease of the heart muscle or myocardium proper. "Variants in ACTA1 associated with combined cardiac and skeletal myopathies have been reported, but ACTA1 represents only ~20% of the total actin pool in cardiomyocytes, making its role in cardiomyopathy controversial." (PMID 40428316, 2025). "ACTA1-associated cardiomyopathies have historically presented alongside skeletal myopathy." (PMID 40225930, 2024). "A full-length human utrophin transgene expressed from a skeletal muscle-restricted promoter/enhancer (Tg(ACTA1-Utrn)2Ked; “Fiona”) was used to rescue the skeletal muscle pathology of dystrophin/utrophin-deficient mice (utrn–/– mdx; dko), allowing progression of cardiomyopathy (Fiona/dko)." (PMID 33651713, 2021). "Terms related to cardiomyopathy are enriched in genes of the foetal gene programme (Acta1 and Myh7) and sarcomere genes." (PMID 41032675, 2025). "The first report of an ACTA1 variant causing cardiomyopathy without clinical skeletal myopathy was reported in 2018." (PMID 40225930, 2024). "In addition, ACTA1 also showed higher methylation levels in gene-body region of HCM patients; ACTA1 has been reported to be associated with cardiomyopathy." (PMID 38780967, 2024). "In addition to LMNA, mutations to CAV3, ACTA1, ACTC1, DYSF, and DSG2 are linked to cardiomyopathies and encode proteins that are long-lived in the heart." (PMID 37162946, 2023). "An associated cardiomyopathy has not been reported in typical CCD due to mutations in the RYR1 gene; however, cardiomyopathies associated with mutations in the MYH7 and the ACTA1 genes may feature central cores on muscle biopsy but do not share the typical clinical features of CCD." (PMID 17504518, 2007).
breast carcinoma (9 papers, 2012 to 2025). "In addition, in basal-like breast cancer, ACTA1 is a biomarker associated with chemotherapy resistance." (PMID 39474352, 2024). "In basal-like breast cancer, ACTA1 is a biomarker associated with chemotherapy resistance." (PMID 39474352, 2024). "Many of these are enzymes or cytoskeletal proteins (ANXA1, KRT10, KRT16, TUBB, ACTB, ACTA1, PKM2, and HSPA8) that have been previously reported as able to induce autoantibodies with diagnostic potential across different tumor types, including PDAC, breast cancer, and neuroblastoma." (PMID 30651550, 2019).
actinopathies (5 papers, 2022 to 2026). "For this reason, diseases caused by ACTA1 variants are broadly termed “ACTA1 disease” or actinopathies." (PMID 40225930, 2024).
centronuclear myopathy (5 papers, 2007 to 2022). Centronuclear myopathy (CNM) is an inherited neuromuscular disorder characterized by clinical features of a congenital myopathy and centrally placed nuclei on muscle biopsy. "It has been reported that severe neonatal bulbar and respiratory muscle involvement occurs particularly in severe NM (most likely ACTA1-, NEB- or KLHL40-related) and MTM1-related myotubular myopathy." (PMID 35081925, 2022).
dilated cardiomyopathy (5 papers, 2007 to 2025). Cardiomyopathy which is characterized by dilation and contractile dysfunction of the left and right ventricles. "Cardiac involvement in ACTA1-related myopathy is rare and has been reported in only a few cases, typically presenting as dilated cardiomyopathy." (PMID 40428316, 2025). "The dilated cardiomyopathy (DCM) pathway involves proteins such as Desmin, DMD, Titin, Tnt, ACTA1, TPM, Laminac, SGCD, TNF-α, IGF-1, TGF-β, and Ang-II." (PMID 32419790, 2020).
head and neck squamous cell carcinoma (5 papers, 2019 to 2023). A squamous cell carcinoma that arises from any of the following anatomic sites: lip and oral cavity, nasal cavity, paranasal sinuses, pharynx, larynx, and salivary glands. "ACTA1 was identified as a biomarker for head and neck squamous cell carcinoma and colorectal cancer." (PMID 36275701, 2022). "The hub gene role of ACTA1 was found in prostate cancer and the prognostic role of ACTA1 was found in head and neck squamous cell carcinoma (HNSCC)." (PMID 33388091, 2021). "ACTA1 is a potential biological indicator of head and neck squamous cell carcinoma." (PMID 37763758, 2023).
hypertrophic cardiomyopathy (5 papers, 2014 to 2024). A condition in which the myocardium is hypertrophied without an obvious cause. "We observed significant upregulation of heart disease markers Myh7, Xirp2, and Acta1, as well as alterations in proteins associated with hypertrophic cardiomyopathy and cardiac muscle contraction, indicating the successful establishment of the MI and TAC models." (PMID 39502510, 2024). "ΔEPORE mice also expressed more than two-fold increased expression of hypertrophic cardiomyopathy-related genes, Acta1, Myh7, Nppa, and Nppb." (PMID 38628440, 2024). "Acta1 expression was also found to be deregulated in a screen measuring cardiac gene expression in patients suffering from hypertrophic cardiomyopathy." (PMID 25280539, 2014). "Moreover, we observed downregulation of Acta1, well-established to be upregulated in hypertrophic cardiomyopathies, in the resting heart." (PMID 36256456, 2022).
muscular dystrophy (5 papers, 2012 to 2024). Muscular dystrophy (MD) refers to a group of more than 30 genetic diseases characterized by progressive weakness and degeneration of the skeletal muscles that control movement. "Many patients with significant respiratory impairment remained ambulant, a feature also shared with early onset SEPN1‐, NEB‐, TPM3‐ ACTA1‐myopathy and COL6‐muscular dystrophy." (PMID 29691892, 2018).